LIMK1 (LIM domain kinase 1)
Diseases named in the same sentence as LIMK1 in open-access papers (continued):
Sharing a sentence is not in itself a finding about the gene and the disease.
Williams syndrome (20 papers, 2012 to 2025). "Recurrent breakage at this fragile site has been implicated in the Williams-Beuren syndrome and and this region contains the genes LIMK1, EIF4H(WBSCR1), AUTS2 as well as the tumor suppressor gene FZD9." (PMID 33444353, 2021). "Normal central nervous system development relies upon the presence of LIMK1, and its deletion has been implicated in the development of the human genetic disorder Williams syndrome." (PMID 35011645, 2021). "Drosophila melanogaster stocks carrying different variants ofthe agnostic locus with changes in the regulatory andstructural regions of the gene encoding LIM kinase 1 (LIMK1) were used tosimulate the human deletion Williams syndrome." (PMID 25093112, 2014). "In the human genome, the LIMK1 gene is located in a region on human chromosome 7 (7q11.23) and is haplodeleted, along with 24 other genes, in adults living with Williams syndrome (WS), a rare neurodevelopmental genetic disorder associated with mild mental retardation (58, –, 60)." (PMID 28381571, 2017). "Interestingly, Williams syndrome, a condition characterized by cognitive impairment, learning difficulties, and cardiovascular disease, is associated with gene deletions at 7q11.2 including the gene for LIMK1." (PMID 25237832, 2014). "Deregulation of LIMK1-dependentactin remodeling is involved in multiple pathologies, such asAlzheimer’s and Parkinson’s diseases, Williams syndrome,schizophrenia, and autism." (PMID 37293442, 2023). "Abnormal LIMK1 expression is also related to mental disorders like the Williams syndrome and Parkinson’s disease." (PMID 33883692, 2021). "In humans, heterozygous deletion of 27 genes, including LIMK1, results in Williams syndrome, a complex developmental disorder characterized by ID and impaired long-term memory." (PMID 34200511, 2021). "There has been considerable interest in LIMK1 in this regard, due to LIMK1's frequent genetic deletion in Williams syndrome and the impaired performance of LIMK1 knockout mice in learning tasks." (PMID 25884247, 2015). "It would seem that the functional role of the LIMK1 enzyme and the geneencoding it in the formation of the Williams syndrome’s pathology hasbeen proved." (PMID 24772323, 2014). "In the mentioned affected family, first step screening revealed deletion of ELN and LIMK1 genes in an 8-year old ID patient, suggestive of Williams-Beuren Syndrome." (PMID 22283845, 2012). "If LIMK1 is a target of miR-134 in humans, and this remains unclear, there might be an application in Williams-Beuren syndrome (WBS), the clinical features of which include locomotor problems and anxiety, although epilepsy is rare." (PMID 35592499, 2022). "According to recent research, several genes within the 7q11.23 chromosomal region may serve as the causes of Williams syndrome, including ELN, LIMK1, and RFC2 genes." (PMID 35011645, 2021). "The LIMK1 gene is related to the impaired visuospatial cognition of Williams syndrome." (PMID 35011645, 2021). "Interestingly, Limk1+/− mice also showed impaired long-term memory, together with reduced late-LTP in the hippocampus, indicating the LIMK1 haploinsufficiency in Williams syndrome patients may be causally related to memory defects." (PMID 34200511, 2021). "We first studied two novel interactions: STX1–DYRK1A and LIMK1–HUNK with STX1 and LIMK1 genes involved in Williams syndrome (WS)." (PMID 35914814, 2022). "It is important to note the genetic context of the general population study results — i.e., no relevant genes are deleted, and the LIMK1 variations we have investigated are common among healthy individuals who do not have Williams syndrome." (PMID 37633900, 2023).
gastric cancer (18 papers, 2014 to 2025). A primary or metastatic malignant neoplasm involving the stomach. "Studies have shown that LIMK1 is frequently upregulated in various cancers, including gastric cancer, and its overexpression is closely associated with enhanced tumor aggressiveness, lower survival rates, and poor prognosis." (PMID 40367093, 2025). "In recent years, abnormal expression and activation of LIMK1 have been widely reported in various cancers, particularly in gastric cancer, where high LIMK1 expression is closely associated with tumor aggressiveness and poor prognosis." (PMID 40367093, 2025). "This research aims to provide a scientific basis for LIMK1-targeted gastric cancer therapy, potentially improving treatment outcomes and patient quality of life." (PMID 40367093, 2025). "This study focuses on the development and optimization of S11a-0000168202, a novel LIMK1 inhibitor with potential therapeutic applications in gastric cancer." (PMID 40367093, 2025). "The distinct overexpression of LIMK1 in gastric cancer makes it a more attractive therapeutic target compared to LIMK2." (PMID 40367093, 2025). "This compound holds significant potential as a therapeutic agent for LIMK1-targeted gastric cancer treatment." (PMID 40367093, 2025). "This study aims to utilize CADD to identify and optimize potential targeted inhibitors against LIMK1 for the treatment of gastric cancer." (PMID 40367093, 2025). "This study focused on the design, optimization, and evaluation of LIMK1 inhibitors, aiming to develop more effective treatments for gastric cancer." (PMID 40367093, 2025). "Collaborations with experimental groups have been initiated to accelerate compound translation.Overall, this compound holds strong potential as a LIMK1-targeted therapeutic agent for gastric cancer, pending further experimental validation." (PMID 40367093, 2025). "Compared to adjacent normal gastric tissue, gastric cancer tissue exhibits upregulated expression of LIMK1, LIMK2, and Cofilin-1, while phosphorylated Cofilin-1 expression is downregulated." (PMID 37946061, 2024). "We first identified LIMK1 as a top overexpressed gene in gastric cancer peritoneal metastasis, examined its functional role in metastatic progression and demonstrated the therapeutic value of targeting LIMK1 in inhibiting gastric cancer peritoneal metastasis." (PMID 33883692, 2021). "Our results imply that LIMK1 inhibition suppressed phosphorylation of cofilin, subsequently reducing cell migration and invasion ability of gastric cancer cells." (PMID 33883692, 2021). "We also first showed that Dabrafenib, an inhibitor of LIMK1, repressed gastric cancer cell migration and invasion in vitro and peritoneal metastasis in vivo." (PMID 33883692, 2021). "To validate the biological function of LIMK1 in gastric cancer metastasis in vivo, we performed experimental metastasis assays in nude mice." (PMID 33883692, 2021). "Taken together, these results indicate that LIMK1 knockout or its pharmacological inhibition with Dabrafenib significantly suppress gastric cancer metastasis to peritoneum and liver." (PMID 33883692, 2021). "Taken together, our results demonstrated that LIMK1 functions as a metastasis promoter in gastric cancer by inhibiting LIMK1-p-cofilin and that Dabrafenib has the potential to serve as a novel treatment for gastric cancer peritoneal metastasis." (PMID 33883692, 2021). "LIMK1 knockout also abrogated peritoneal and liver metastases of gastric cancer cells in nude mice in vivo." (PMID 33883692, 2021). "To investigate biological function of LIMK1 in gastric cancer, we performed CRISPR/Cas9 to knockout LIMK1 in MKN74 cells with 2 sgRNA." (PMID 33883692, 2021). "Using transcriptomic sequencing of paired gastric cancer peritoneal metastasis, primary tumors, and normal gastric tissues, we first unveiled that LIMK1 is selectively up-regulated in metastatic tumors." (PMID 33883692, 2021).
gastric cancer (continued). "We demonstrated that LIMK1 promotes gastric cancer cell migration and invasion, leading to enhanced peritoneal metastasis in mice models." (PMID 33883692, 2021). "Independent cohort validation showed that LIMK1 is a top gene candidate overexpressed in metastatic gastric cancer." (PMID 33883692, 2021). "Increased LIMK1 in gastric cancer peritoneal metastasis was validated by immunohistochemistry analysis of an independent patient cohort." (PMID 33883692, 2021). "We next performed wound healing and transwell migration assays to assess the effect of LIMK1 on gastric cancer cell migration." (PMID 33883692, 2021). "In vitro functional studies demonstrated that LIMK1 knockout or knockdown significantly inhibited cell migration and invasion of gastric cancer cells." (PMID 33883692, 2021). "Dabrafenib, a small molecule targeting LIMK1, was found to decrease cell migration and invasion of gastric cancer cells in vitro and abolish peritoneal and liver metastasis formation in vivo." (PMID 33883692, 2021). "We further proved the function of LIMK1 in promoting cell migration and invasion in gastric cancer cells (MKN74 and BGC823) in vitro; and in xenograft nude mice models of peritoneal and liver metastasis in vivo." (PMID 33883692, 2021). "LIMK1 mediates metastasis by promoting phosphorylation of its downstream target cofilin, leading to increased gastric cancer cell migration and invasion." (PMID 33883692, 2021). "In summary, transcriptome profiling has unveiled LIMK1 as a novel promoter of gastric cancer peritoneal metastasis." (PMID 33883692, 2021). "Taken together, Dabrafenib suppressed gastric cancer peritoneal metastasis through inhibition of LIMK1." (PMID 33883692, 2021). "Transwell matrigel invasion assay was next performed to assess the effect of LIMK1 on gastric cancer cell invasion." (PMID 33883692, 2021). "In this study, we reported the identification of LIM domain kinase 1 (LIMK1) as a promoter of gastric cancer peritoneal metastasis, and its potential to be a therapeutic target of dabrafenib (DAB)." (PMID 33883692, 2021). "We first verified that DADS inhibited cell migration and decreased LIMK1 protein expression in the human gastric cancer line MGC803." (PMID 26871290, 2016). "We have previously discovered that it has a repressive effect on LIM kinase-1 (LIMK1) expression in gastric cancer MGC803 cells." (PMID 26871290, 2016). "Recent studies have shown that inhibiting Rac1 activity or knocking down LIMK1 expression abrogated their effects on malignant phenotypes, including increased growth and invasion in gastric cancer cells." (PMID 26871290, 2016). "Therefore, further exploration and optimization of LIMK1 inhibitors are crucial for the treatment of gastric cancer." (PMID 40367093, 2025). "LIMK1 plays a crucial role in cytoskeletal dynamics, influencing cell migration, invasion, and tumor progression, especially in aggressive forms of cancer such as gastric cancer." (PMID 40367093, 2025). "The expression of LIMK1 is significantly elevated in peritoneal metastatic tissues from patients with gastric cancer, and the knockout of LIMK1 can result in migration and invasion retardation of gastric cancer cells." (PMID 36836593, 2023). "LIMK1 is a serine/threonine-protein kinase that plays an essential role in the regulation of actin filament dynamics, however; its role in gastric cancer peritoneal metastasis is largely unknown." (PMID 33883692, 2021). "Finally, we identified Dabrafenib as a LIMK1 inhibitor that can suppress gastric cancer peritoneal metastasis in experimental models." (PMID 33883692, 2021). "We therefore determined the role of LIMK1 in gastric cancer peritoneal metastasis." (PMID 33883692, 2021). "In light of the role of LIMK1 in promoting cell migration and invasion in gastric cancer cells, we further investigated whether LIMK1 inhibitors could suppress cell migration and invasion in vitro." (PMID 33883692, 2021).
gastric cancer (continued). "Moreover, GL-1196 prominently inhibited the invasion of human gastric cancer cells in parallel with blockage of the PAK4/LIMK1/cofilin pathway." (PMID 27077843, 2016). "Thus, DADS inhibits EMT, invasion and proliferation by downregulating LIMK1 in gastric cancer cells." (PMID 26871290, 2016). "This suggests that DADS may inhibit epithelial-mesenchymal transition (EMT) by downregulating LIMK1, resulting in the inhibition of invasion and growth in gastric cancer." (PMID 26871290, 2016). "Thus, LIMK1 has emerged as a promising molecular target for gastric cancer treatment." (PMID 40367093, 2025). "Therefore, LIMK1 promotes EMT in gastric cancer cells, and this process can be reversed by DADS." (PMID 26871290, 2016). "We therefore hypothesized that LIMK1 might be involved in DADS-induced inhibition of EMT, invasion and proliferation in gastric cancer cells." (PMID 26871290, 2016). "Therefore, the downregulation of LIMK1 may result in DADS-induced changes in the expression of these proteins and inhibit proliferation in gastric cancer." (PMID 26871290, 2016).
Cognitive impairment (15 papers, 2014 to 2026). Abnormal cognition is characterized by deficits in thinking, reasoning, or remembering. "Recent studies have shown that the downregulation of LIMK1 by miR-27b is associated with cognitive impairment in response to sevoflurane." (PMID 36313620, 2022). "Indeed, although LIMK2 shares 50% identity overall (70% identity in the kinase domain) with LIMK1 and is present in the brain, it cannot replace LIMK1, as highlighted by the presence of spine abnormalities and cognitive deficits observed in LIMK1 knockout mice and humans with LIMK1 mutations." (PMID 40461464, 2025). "Interestingly, LIMK1 appears particularly important for actin regulation in spines, because LIMK1 knockout in mice or genetic mutation in humans is associated with spine abnormalities and cognitive impairments." (PMID 25884247, 2015). "Moreover, although LIMK1's upstream activator in neurons is unclear, spine abnormalities and intellectual impairments are also linked to mutations in PAK3, a member of the p21-activated kinase (PAK) family that phosphorylates and activates LIMK1 in non-neuronal cells." (PMID 25884247, 2015). "PirB knockdown alleviated synaptic deficits and cognitive impairment after CSR by inhibiting the RhoA/ROCK2/LIMK1/cofilin signalling pathway." (PMID 36417104, 2023). "Subsequently, miR-106a upregulation was found to decrease Bcl-2 levels, increase expression levels of Bax and cleaved caspase 3, and exacerbate isoflurane-induced cognitive impairment by targeting LIMK1." (PMID 36313620, 2022). "In another research, authors considered that neuroprotection of LPIN1 was associated with inhibition of the PKD/Limk1/Cofilin signaling pathway, and LPIN1 might ameliorate the cognitive impairments in Diabetic encephalopathy (DE) animal models." (PMID 36918862, 2023). "It is possible that changes in LIMK1/cofilin is region/cell-specific, so that global and region/cell cell-specific manipulations of LIMK1 may have different effects on synaptic and cognitive impairments in these mice." (PMID 34315506, 2021). "Altogether, these data reveal that CSR-mediated activation of the RhoA/ROCK2/LIMK1/cofilin signalling cascade via the PirB receptor may result in abnormal actin dynamics and actin rearrangement, ultimately leading to synaptic deficits and cognitive impairment." (PMID 36417104, 2023). "The study aimed to investigate whether miRNAs/LIMK1 signaling was involved in electroacupuncture- (EA-) mediated synaptic-dendritic plasticity in a rat model of middle cerebral artery occlusion induced cognitive deficit (MICD)." (PMID 28116173, 2017). "Finally, spine-associated impairments in the absence of palmitoyl-LIMK1 are reminiscent of phenotypes seen in human patients with Intellectual Disability and other cognitive disorders." (PMID 25884247, 2015). "Because the expression of LIMK1 is restricted to the hippocampal excitatory neurons, our results reveal that increased cofilin activity in hippocampal excitatory neurons may be particularly important for early synaptic and cognitive deficits in APP/PS1 transgenic mice." (PMID 34315506, 2021). "Moreover, we identified that fasudil could mimic the beneficial effect of PirB knockdown and ameliorate synaptic deficits and cognitive impairment, which further demonstrated that the RhoA/ROCK2/LIMK1/cofilin signalling pathway is downstream of PirB in CSR." (PMID 36417104, 2023). "Moreover, we found that fasudil, a widely used ROCK2 inhibitor, could mimic the beneficial effect of PirB knockdown and ameliorate synaptic deficits and cognitive impairment, further demonstrating that PirB induced cognitive dysfunction after CSR via the RhoA/ROCK2/LIMK1/cofilin signalling pathway." (PMID 36417104, 2023).
pancreatic cancer (14 papers, 2011 to 2023). "Among these we found that up regulation of S100A4, NCAM1 and LIMK1 had already been associated with metastatic behavior in pancreatic cancer." (PMID 22078386, 2011). "In pancreatic cancer, Vlecken and Bagowski (2009) reported that knockdown of LIMK1 can lead to an inhibition of invasion and metastatic behavior, as well as suppression of pancreatic cancer cell-induced angiogenesis." (PMID 34149814, 2021). "In a recent research, LINC00941 was shown to enhance pancreatic cancer growth by competing with miR-335-5p to inhibit the ROCK1-mediated LIMK1/cofilin-1 signaling pathway." (PMID 34764994, 2021). "More recently, role of LIMK1 in induction of metastasis in pancreatic cancer in zebrafish xenograft assays; and mesenchymal and ameboid modes of invasion of fibrosarcoma cells in 3D matrices were shown." (PMID 21219645, 2011). "In pancreatic cancer, LINC00941 has shown to activate the LIMK1/Cofilin-1 pathway, which enhances cell proliferation and migration by regulating the actin cytoskeleton." (PMID 36869839, 2023). "Research on zebrafish has confirmed that LIMK1 and LIMK2 lead to pancreatic cancer metastasis and angiogenesis." (PMID 29970879, 2018). "LIMK1 and LIMK2 are important for pancreatic cancer cell metastasis and tumor cell-induced angiogenesis." (PMID 27902487, 2017). "Recent studies demonstrate an important role for both LIMK1 and LIMK2 in pancreatic tumor progression, cancer cell-induced angiogenesis, and metastasis formation." (PMID 25593987, 2014).
hepatocellular carcinoma (11 papers, 2013 to 2022). A malignant tumor that arises from hepatocytes. "The diagnostic accuracy of LIMK1 in the diagnosis of hepatocellular carcinoma was higher than that of AFP." (PMID 32168432, 2020). "Knockout of LIMK1 inhibits migration and invasion of hepatocellular carcinoma cells from rat peritoneal effusion." (PMID 35265128, 2022). "In addition, recent investigations suggest that nuclear LIMK1 can bind to the promoter of c-myc to upregulate c-myc transcription in hepatic carcinomas, and c-myc overexpression has been shown to promote fibrogenesis in hepatic stellate cells." (PMID 34769418, 2021). "Cytoplasmic p57 might be a key regulator in hepatocellular carcinoma invasion via the LIM domain kinase 1/p-cofilin pathway." (PMID 26271467, 2015). "Therefore, we propose that the DANCR/miR‐27a‐3p/LIMK1 axis may have great influence in hepatocellular carcinoma progress." (PMID 31038266, 2019).